ZNF816 (zinc finger protein 816)
Description:
May be involved in transcriptional regulation.
Synonyms: ZNF816A
Tractability: PROTAC: ubiquitination databases record sites on it.
Gene: Protein-coding gene on chromosome 19 (52,949,377 to 52,962,911, reverse strand). Ensembl gene ENSG00000180257.
Subcellular location: Nucleus
Subcellular location (Human Protein Atlas): Nucleoli rim
Pathways (Reactome):
Gene expression (Transcription): Regulation of endogenous retroelements by KRAB-ZFP proteins
Gene Ontology:
Molecular function: DNA-binding transcription factor activity, RNA polymerase II-specific; RNA polymerase II cis-regulatory region sequence-specific DNA binding; DNA-binding transcription factor activity; sequence-specific double-stranded DNA binding
Biological process: regulation of transcription by RNA polymerase II; negative regulation of transcription by RNA polymerase II; regulation of DNA-templated transcription
Cellular component: nucleus
Genetic constraint (gnomAD): Loss-of-function variants: 12 observed, 9.78 expected, observed/expected ratio (o/e) 1.23, 90% interval 0.78 to 1.83. That is too few expected variants to judge how well the gene tolerates losing a copy. Missense variants: 710 observed, 805.78 expected, observed/expected ratio (o/e) 0.88, 90% interval 0.83 to 0.94. Synonymous variants: 255 observed, 260.62 expected, observed/expected ratio (o/e) 0.98, 90% interval 0.88 to 1.09.
Homologues: Orthologues: chimpanzee ZNF816 (93% identical), macaque ZNF816 (86% identical). Paralogues in human: ZNF813 (66% identical), ZNF761 (64% identical), ZNF888 (62% identical), ZNF860 (62% identical), ZNF578 (61% identical), ZNF765 (53% identical), ZNF468 (52% identical), ZNF525 (49% identical), ZNF701 (46% identical), ZNF766 (35% identical).
Diseases named in the same sentence as ZNF816 in open-access papers:
ZNF816 is named in the same sentence as 3 diseases in open-access papers, as found by Europe PMC text mining. Sharing a sentence is not in itself a finding about the gene and the disease.
ZNF816 shares sentences with these, for which no sentence is quoted: psoriasis (3 papers); autoimmune disease (1); plaque psoriasis (1).